ZNHIT6 (zinc finger HIT-type containing 6)
Description:
Required for box C/D snoRNAs accumulation involved in snoRNA processing, snoRNA transport to the nucleolus and ribosome biogenesis.
Synonyms: BCD1; C1orf181; FLJ20729; NY-BR-75
Tractability: PROTAC: UniProt records ubiquitination sites on it; ubiquitination databases record sites on it.
Gene: Protein-coding gene on chromosome 1 (85,649,417 to 85,708,433, reverse strand). Ensembl gene ENSG00000117174.
Subcellular location (Human Protein Atlas): Nuclear speckles; Vesicles
Gene Ontology:
Molecular function: ATPase binding; enzyme binding; identical protein binding; protein binding; TFIID-class transcription factor complex binding
Biological process: box C/D snoRNP assembly; protein complex oligomerization; snoRNA localization; maturation of LSU-rRNA from tricistronic rRNA transcript (SSU-rRNA, 5.8S rRNA, LSU-rRNA)
Cellular component: extracellular exosome; pre-snoRNP complex; nucleus
Genetic constraint (gnomAD): Loss-of-function variants: 21 observed, 36.71 expected, observed/expected ratio (o/e) 0.57, 90% interval 0.41 to 0.82. The upper end of that interval is the gene's LOEUF score, 0.82, which puts it in group 3 of 6, group 1 being the genes least tolerant of losing a copy. Missense variants: 379 observed, 444.33 expected, observed/expected ratio (o/e) 0.85, 90% interval 0.78 to 0.93. Synonymous variants: 138 observed, 153.18 expected, observed/expected ratio (o/e) 0.9, 90% interval 0.78 to 1.04.
Homologues: Orthologues: chimpanzee ZNHIT6 (99% identical), macaque ZNHIT6 (94% identical), dog ZNHIT6 (77% identical), guinea pig ZNHIT6 (74% identical), rabbit ZNHIT6 (74% identical), mouse Znhit6 (71% identical), pig ZNHIT6 (71% identical), rat Znhit6 (71% identical), tropical clawed frog znhit6 (33% identical), zebrafish znhit6 (25% identical), Drosophila melanogaster CG1463 (16% identical), Caenorhabditis elegans zhit-3 (14% identical).
Diseases named in the same sentence as ZNHIT6 in open-access papers:
ZNHIT6 is named in the same sentence as 4 diseases in open-access papers, as found by Europe PMC text mining. Sharing a sentence is not in itself a finding about the gene and the disease. The quoted sentences say what the papers report.
breast carcinoma (1 paper, 2016). "Among these genes, ZNHIT6 and SLC39A1 have been linked to prostate or breast cancer." (PMID 26951498, 2016).
emphysema (1 paper, 2009). "The candidate genes (CDKN2A, GSTM3, COL6A3, SERPINF1, NRN1, NEDD4 and ZNHIT6) had ontologies that were relevant to emphysema progression, including cell cycle regulation (CDKN2A), collagen (COL6A3), anti-angiogenesis (SERPINF1) and oxidative stress (GSTM3)." (PMID 19723343, 2009). "Gene expression profiling of lung from emphysema patients identified seven candidate genes associated with emphysema severity including COL6A3, SERPINF1, ZNHIT6, NEDD4, CDKN2A, NRN1 and GSTM3." (PMID 19723343, 2009).
ZNHIT6 also shares sentences with these, for which no sentence is quoted: diffuse large B-cell lymphoma (1 paper); Sepsis (1).